CASP9 (caspase 9)
Diseases named in the same sentence as CASP9 in open-access papers (continued):
Sharing a sentence is not in itself a finding about the gene and the disease.
colitis (6 papers, 2012 to 2024). Inflammation of the colon. "In spite of this, SM934 regulated the balanced Bcl-2 and BAX, and cleaved caspase-9 and cleaved caspase-3 in colitis, and also downregulated the cleaved caspase-3 in TNF-α-induced IEC apoptosis in vitro." (PMID 36120344, 2022). "BMSC-EVs also suppressed the apoptosis via reducing the cleavage of caspase-3, caspase-8 and caspase-9 in colitis rats." (PMID 26469068, 2015). "Another study has reported that bone mesenchymal stem cells (BMSCs) derived exosome could suppress the apoptosis via reducing the cleavage of caspase-3, caspase-8, and caspase-9 directly in colitis rats." (PMID 31534118, 2019). "The mRNA level of Bcl-2 was slightly increased, and the anti-apoptosis genes Bax, caspase-9, and caspase-3 largely decreased in SM934-treated colitis mice." (PMID 36120344, 2022).
COVID-19 (6 papers, 2022 to 2025). A disease caused by infection with severe acute respiratory syndrome coronavirus 2. "Regarding the regulation of apoptosis molecules, caspase-3, caspase-9, Bcl-2, and Bax are essential factors in alleviating LC, PF, and COVID-19." (PMID 37007037, 2023). "Literature describes CASP9 as an antagonist to the pyroptosis process observed in our COVID-19 group." (PMID 36361818, 2022). "Regarding the immunohistochemical analysis, there was a statistically significant difference in the expression of the following markers, with higher concentrations in control group B compared to COVID-19 group A: IL-6 (p < 0.0001), IL-18 (p = 0.002), CASP-9 (p < 0.0001), and HIF (p = 0.0327)." (PMID 40004007, 2025). "Consistent with the apoptosis trend of Tim-3+ NKT cells, an elevated expression level of almost all caspase genes in Tim-3+ NKT cells was observed in controls and patients with mild and severe COVID-19, especially caspase-2, caspase-3, caspase-6, and caspase-9." (PMID 35250975, 2022). "CASP9 is an apoptosis mediator and was chosen as a negative control for inflammasome activation; it was found to be less expressed in the COVID-19 group when compared to the control group (p < 0.0001)." (PMID 36361818, 2022). "In contrast, people with obesity without COVID-19, despite exhibiting some markers of the NLRP3 inflammasome, are more likely to experience necroptosis mediated by caspase-9." (PMID 40004007, 2025). "Conversely, though individuals with obesity and without COVID-19 exhibit markers of the NLRP3 inflammasome, the main mechanism of cell death is more likely necroptosis, not pyroptosis, mediated by caspase-9, a non-inflammatory form of cell death, non-related to the NLRP3 inflammasome pathway." (PMID 40004007, 2025). "We observed that the patients suffering from COVID-19 underwent a process of cell death called pyroptosis, which is dependent on inflammasome activation and shows a very specific caspase expression, relying on CASP1 (but not CASP9)." (PMID 36361818, 2022).
myeloid leukemia (6 papers, 2012 to 2022). A clonal proliferation of myeloid cells and their precursors in the bone marrow, peripheral blood, and spleen. "With regard to apoptosis, specific silencing of WT1(+17AA) by siRNA induced apoptosis via activation of caspase-3 and caspase-9 in myeloid leukemia cells." (PMID 33110919, 2020). "Meanwhile, the activity of caspase-9 and caspase-3 was higher than in the BL or GRh2 groups, while the GRh2 group had higher levels of myeloid leukemia cells than the BL group." (PMID 35540666, 2019). "It is also worth mentioning that the addition of a caspase-9 inhibitor clearly compromised the apoptogenic activity of AD0157 on the myeloid leukemia cells." (PMID 29163182, 2017).
psoriasis (6 papers, 2018 to 2024). An autoimmune condition characterized by red, well-delineated plaques with silvery scales that are usually on the extensor surfaces and scalp. "In terms of the dysfunctional apoptosis brought on by psoriasis, the expression of caspase-9 in the SS/PVA and Cal/PVA groups was significantly lower than that seen in the untreated group." (PMID 36613589, 2022). "We found that the interaction of CASP10 - CASP1, CASP10- CASP3, CASP10- CASP4, CASP10- CASP9, CASP10- CASP12, CASP8 - CASP3, CASP8 - CASP4, and CASP1 - CASP12 is important for the risk of psoriasis." (PMID 30906769, 2019). "As PGAM5 activates mainly caspase 9, it may be responsible for its activation in psoriasis." (PMID 34576119, 2021). "At the same time, the apoptosis-promoting mechanisms are disturbed in psoriasis, as psoriatic skin is resistant to INF-γ, is characterized by lowered levels of caspase-9, and displays an imbalanced expression of apoptosis regulatory molecules." (PMID 38672088, 2024).
triple-negative breast carcinoma (6 papers, 2019 to 2025). An invasive breast carcinoma which is negative for expression of estrogen receptor (ER), progesterone receptor (PR), and human epidermal growth factor receptor 2 (HER2). "In triple-negative breast cancer, Mir-224 has been shown to downregulate caspase-9 expression and promote tumor growth." (PMID 35846123, 2022). "In our investigation, we aimed to explore the impact of caspase-9 on the migration and invasion behaviors of MDA-MB-231, a triple-negative breast cancer (TNBC) cell line known for its metastatic properties." (PMID 38956424, 2024). "Besides, we found that CASP9 was strongly elevated in non-basal-like subtype with respect to basal-like subtype; the same pattern of change was also observed in triple-negative breast cancer (TNBC) patients." (PMID 36199443, 2022).
cholangiocarcinoma (5 papers, 2022 to 2024). A carcinoma that arises from the intrahepatic biliary tree (intrahepatic cholangiocarcinoma) or from the junction, or adjacent to the junction, of the right and left hepatic ducts (hilar cholangiocarcinoma). "Cytochrome C was significantly decreased within the mitochondria, but increased in the cytoplasm after silibinin administration, which further activated downstream Caspase-9, causing cholangiocarcinoma cell apoptosis." (PMID 35401195, 2022). "Furthermore, we discovered that expression of cleaved Caspase-9 significantly increased after silibinin administration, which implies that apoptosis of cholangiocarcinoma cells may be mitochondria-related." (PMID 35401195, 2022). "Tumor immunohistochemistry showed that nude mice transplanted with human cholangiocarcinoma cells treated with Lan C exhibited decreased STAT3 expression and increased caspase-9 and caspase-3 expression in tumors, consistent with the in vitro results." (PMID 37397486, 2023). "extended the apoptotic activity of USP8 in cholangiocarcinoma cells, where the silencing of USP8 was reported to decrease Bcl-2 expression and increase Bax, cleaved Caspase 3, and cleaved Caspase 9 expression and thereby triggering apoptosis." (PMID 36338727, 2022). "According to in vivo research, allicin 10 and 20 mg/kg was administered, i.e., daily for 4 weeks, and it increased the apoptotic caspases that were produced in Cholangiocarcinoma (CCA) by suppressing STAT3 signalings, such as cleaved caspase-3 and cleaved caspase-9." (PMID 38542956, 2024). "After NAC pretreatment, STAT3 expression was not downregulated in cholangiocarcinoma cells, the expression of p-STAT3 was significantly increased compared with Y3 group, and caspase-3, caspase-9, cleaved PARP expression were significantly inhibited." (PMID 37397486, 2023).
chondrosarcoma (5 papers, 2016 to 2024). A malignant cartilaginous matrix-producing mesenchymal neoplasm arising from the bone and soft tissue. "To further validate the effect of miR-6839-5p on apoptosis, we examined the expression of Bcl-2, Bax, cleaved caspase-3, and cleaved caspase-9 apoptotic proteins in chondrosarcoma cells by Western blotting assay." (PMID 38762695, 2024). "Our results indicate that calpains, caspase-3/7, and caspase-9 activation is involved in the ACDB-mediated human chondrosarcoma cell apoptosis." (PMID 27835579, 2016). "Upstream caspase-3 and caspase-9 activities increased significantly, as shown by the observation that treatment with BL-038 (5 μM) increased caspase-3 and caspase-9 activity in chondrosarcoma cells." (PMID 27618007, 2016). "Surprisingly, in the three chondrosarcoma cell lines, miR-342-5p also had anti-apoptotic effects, because it tended to decrease (by 1.2-fold) the protein expression of the Bak pro-apoptotic protein, and that of the pro-caspase-9 (at least 3-fold)." (PMID 34070455, 2021). "However, in the three chondrosarcoma cell lines, it caused a strong decrease (at least 3-fold) in pro-caspase-9 protein expression (47 kDa), without induction of the large cleaved caspase-9 fragments (37 and 35 kDa)." (PMID 34070455, 2021). "In our study, cleaved caspase-9 was not clearly observed in all chondrosarcoma cell lines, even with miR-491-5p, whose activation of the intrinsic apoptosis pathway has already been demonstrated." (PMID 34070455, 2021). "Therefore, our data suggest that caspase-3/7, caspase-9, and cleaved-PARP activation is involved in the ACDB-mediated human chondrosarcoma cell apoptosis." (PMID 27835579, 2016).
endothelial dysfunction (5 papers, 2016 to 2022). In vascular diseases, endothelial dysfunction is a systemic pathological state of the endothelium (the inner lining of blood vessels) and can be broadly defined as an imbalance between vasodilating and vasoconstricting substances produced by (or acting on) the endothelium. "Moreover, Casp9 iEC KO mice have less neuronal TUNEL 24 h post-RVO, indicating that caspase-9 mediated endothelial dysfunction drives neuronal injury in RVO." (PMID 32576823, 2020). "RVO-induced caspase activation in neurons is driven by caspase-9 mediated endothelial dysfunction." (PMID 32576823, 2020). "Caspase-9/3 activity was analyzed to determine the mechanism of endothelial dysfunction." (PMID 27918592, 2016). "Other factors can also be at play, for example, in a mouse model of retinal vein occlusion, activated ECs expressed caspase-9, the caspase-9 induced non-apoptotic endothelial dysfunction, and barrier breakdown." (PMID 32848875, 2020). "Since caspase-9 can contribute to both apoptotic and nonapoptotic endothelial dysfunction, examining regulation of caspase-9 activity in different vascular pathologies may give insight into endothelial physiology and vascular health." (PMID 34305609, 2021).
head and neck squamous cell carcinoma (5 papers, 2012 to 2025). A squamous cell carcinoma that arises from any of the following anatomic sites: lip and oral cavity, nasal cavity, paranasal sinuses, pharynx, larynx, and salivary glands. "Results showed that oprozomib induced apoptotic pathway through Bik upregulation and activation of caspase-8, caspase-9, caspase-3, and PARP cleavage in head and neck squamous cell carcinoma (HNSCC) cells, leading to cell death." (PMID 29134486, 2017).
ischemic stroke (5 papers, 2016 to 2024). A stroke disorder caused by obstruction of blood flow to the brain, due to thrombotic (local blood clot formation) or embolic (due to a blood clot or other material traveling from another site) event. "Additionally, the A28V/G mutation in caspase-9 has been associated with decreased risk of ischemic stroke, supporting a possible causative connection between caspase-9 and vascular disease." (PMID 34305609, 2021). "It not only suppressed inflammatory response states in astrocytes following ischemic stroke by targeting lipocalin 2 (LCN2) but also inhibited the target of caspase-9 and apoptosis-related cysteine peptidase (Casp9) against ischemic stroke (IS) injury." (PMID 37841310, 2023). "Meanwhile, caspase-9 cleavage of caspase-6 contributes to axonal degeneration in ischemic stroke." (PMID 34305609, 2021).
malaria (5 papers, 2012 to 2023). Malaria is a serious and sometimes fatal disease caused by a parasite that commonly infects a certain type of mosquito which feeds on humans. "Moreover, the activation of caspase 9 in malaria infected placenta also indicated the occurrence of mitochondrial pathway of apoptosis." (PMID 22396790, 2012).
myocardial infarction (5 papers, 2015 to 2025). Gross necrosis of the myocardium, as a result of interruption of the blood supply to the area, as in coronary thrombosis. "The WB results indicated that acute myocardial infarction caused by ligation of the left coronary artery induced an increase in cleaved caspase-9/procaspase-9 ratio (2.34 ± 0.17 versus 1.00) and cleaved caspase-3/procaspase-3 ratio (7.64 ± 0.77 versus 1.00) compared with SHAM group." (PMID 29279737, 2017). "In a previous study, treatment with I3C was found to improve cardiac function in a rat myocardial infarction model by reducing the expression of apoptotic markers such as cytochrome C, caspase-9, and caspase-3." (PMID 35734410, 2022). "The I/R aggravated cardiomyocytes damage, apoptosis and myocardial infarct size, reduced cardiac function, increased the level of Bcl-2, caspases-3 and caspase-9 mRNA, the mitochondrial release of Cyt c and oxidative stress in the aging hearts." (PMID 25789157, 2015). "Studies have demonstrated that exosomes derived from bone marrow MSCs (BMSC-Exo) overexpressing miR-30e can ameliorate myocardial infarction in rats by inhibiting LOX-1 expression and downregulating NF-κB p65/Caspase-9 signaling, thereby reducing myocardial pathological damage and fibrosis." (PMID 40642081, 2025).
Obesity (5 papers, 2020 to 2026). Accumulation of substantial excess body fat. "Immunohistochemistry (IHC) analysis further indicated that caspase-3 and caspase-9 expression levels were significantly downregulated in the obesity group, suggesting impaired liver regeneration in obese rats." (PMID 41493825, 2026). "Obesity aggravates myocardial dysfunction by releasing caspase 9/3, Cyt-c, and Bad proteins and increases oxidative stress." (PMID 38397916, 2024). "Obesity aggravates myocardial mitochondrial dysfunction following AMI by increasing the mRNA expression of caspase 9/3, Cyt-c, and PARP and decreasing the mRNA expression of PI3K, Bad, and Akt." (PMID 38397916, 2024). "IR and IR+obesity can significantly activate Caspase-9/3, particularly the IR+obesity (p < 0.05)." (PMID 36279396, 2022). "Transcript level of pro-apoptotic molecules such as cMyc, Casp9 and Bax were increased, whereas the level of Bcl-2 mRNA was decreased in MAIT cells during obesity." (PMID 32709874, 2020).
renal carcinoma (5 papers, 2014 to 2025). A carcinoma arising from the epithelium of the renal parenchyma or the renal pelvis. "Complementing these observations, SMR analysis suggests a genetic contribution of CASP9 to renal cancer risk." (PMID 41201629, 2025). "To explore the genetic regulatory mechanisms linking CASP9 expression to renal cancer risk, we conducted SMR analysis integrating GWAS and eQTL datasets." (PMID 41201629, 2025). "This integrative strategy enabled us to not only map CASP9-high malignant states within macrophage-rich niches, but also to demonstrate a genetic contribution of CASP9 to renal cancer susceptibility." (PMID 41201629, 2025). "Stimulation of caspase-9 caused the activation of caspase-3 and caspase-7 and led to cellular apoptosis in renal cancer cells." (PMID 34745413, 2021). "SMR was employed to link genetically regulated CASP9 expression with renal cancer risk." (PMID 41201629, 2025). "SMR analysis provided genetic evidence supporting CASP9 as a causal gene for renal cancer." (PMID 41201629, 2025). "Suppressing the activation of caspase-9 downstream can cause chemotherapy resistance in diffuse large B-cell lymphoma; overexpression of the inhibitor of caspase-3 can activate deoxyribonuclease in human renal carcinoma cells, therefore enhancing their resistance to cytotoxic chemotherapy." (PMID 25086656, 2014). "Our findings not only elucidate the complex role of apoptosis in ccRCC pathogenesis but also provide a foundation for future mechanistic investigations into the molecular pathways linking CASP9 dysregulation to renal cancer progression." (PMID 41201629, 2025). "Among these genes specific to Cox-nnet, many have been previously reported to relevant to renal carcinoma development and prognosis, such as CASP9, TGFBR2, KDR (VEGFR)." (PMID 29634719, 2018). "Collectively, these results support the hypothesis that CASP9 expression is genetically regulated and may act as a functional driver of renal cancer development, providing genetic evidence for its role in tumorigenesis." (PMID 41201629, 2025). "CASP9 (ENSG00000132906) was identified as a significant candidate gene with a notable pSMR value below the 0.05 threshold, indicating a potential causal relationship between its genetically regulated expression and renal cancer susceptibility." (PMID 41201629, 2025). "CACNA1D (Voltage-dependent L-type calcium channel subunit alpha-1D) is lowly expressed in RCC, and the expression level of CASP9 (Caspase-9) is altered in RCC by rs12124078 SNP, while CTSG (Cathepsin G) inhibition enhances apoptosis in human renal carcinoma (Caki) cells." (PMID 33573278, 2021).
retinal detachment (5 papers, 2013 to 2024). An eye emergency condition which may lead to blindness if left untreated. "The study associated increased levels of cl-caspase-9 with severity and duration of retinal detachment." (PMID 34305609, 2021). "Three days after retinal detachment, caspase 3, caspase 8 and caspase 9 were significantly activated in the detached retina." (PMID 24040416, 2013). "Retinal detachment was reduced only in eyes treated with caspase-9 inhibitor monotherapy." (PMID 37449272, 2023). "XIAP overexpression confers neuroprotection in rodent and feline injury models, and pharmacological inhibition of caspase-9 by Pen1-XBir3 reduces severity of retinal detachment in mouse retinal vein occlusion, supporting caspase-9 activity as a potential therapeutic target for retinal detachments." (PMID 34305609, 2021). "Our previous works have shown that in mouse models of retinal detachment and AMD, treatment by Met12, a precursor molecule to INL1204, inhibited Fas-mediated caspase 8 activation, and reduced activities of caspase 3 and caspase 9 as well." (PMID 39117629, 2024).
Stroke (5 papers, 2012 to 2024). Sudden impairment of blood flow to a part of the brain due to occlusion or rupture of an artery to the brain. "Male MMP-3 KO stroke brains also exhibited downregulation of apoptosis-related genes such as Casp9, Casp7, Bmf, Casp1, Bid, Casp6, Casp3, Casp2, Fas, Casp4, and Casp8." (PMID 39000490, 2024). "In the stroke model, caspase-9 levels were lower in the P/D@Mn/Co3O4 nasal administration group than in the control group, indicating a decrease in apoptosis via the mitochondrial pathway." (PMID 37567914, 2023). "CASP3 was augmented 24 h after stroke in the core of the lesion, whereas CASP9 and AIFM3 levels were decreased after cerebral infarct in both core and PI areas, but these differences with normal levels were not significant in the PI area 3 d after the lesion." (PMID 23284893, 2012).
breast tumors (4 papers, 2010 to 2026). "Also, a pro-inflammatory microenvironment associated with tumor derived NOS2 directly correlated with tumor pAkt status and downstream signaling including p-caspase-9 and pBAD in the same breast tumors." (PMID 22957045, 2012).